BNIP3L (BCL2 interacting protein 3 like)
Diseases named in the same sentence as BNIP3L in open-access papers (continued):
Sharing a sentence is not in itself a finding about the gene and the disease.
lung carcinoma (6 papers, 2007 to 2026). "We detected a significant elevation of BNIP3 and BNIP3L expression in lung cancer cells in a dose-dependent manner upon CVB-D treatment." (PMID 34072333, 2021). "To further explore the underlying mechanism involved in CVB-D-induced mitophagy, we first detected the expression of parkin/Pink1 and BNIP3/BNIP3L in lung cancer cells upon CVB-D treatment." (PMID 34072333, 2021). "Similar to lung cancer we found BNIP3L to be downregulated in metastases and tumour invasion front in our model, underlining its pivotal role in apoptosis." (PMID 17940512, 2007).
viral infection (6 papers, 2020 to 2025). "Concurrently, genes associated with hypoxic stress, including PDK1, BNIP3L, VEGF, and LOX, were significantly upregulated in both EBOV- and MARV-infected HCOs, consistent with prior reports of hypoxia-related signaling during viral infection." (PMID 41284734, 2025). "During viral infection, both NIX/BNIP3L and BNIP3 are required for the generation of natural killer (NK) memory and the enhancement of NK cell proliferation through protective mitophagy activation via the Atg3-dependent mechanism." (PMID 32630319, 2020). "Additionally, BNIP3L was elevated in bacterial infection, potentially reflecting its role in mitophagy, while DNMT1, IFI27, SLFN5, and AHNAK were elevated in viral infection, and PABPC4 was elevated in KD." (PMID 39240972, 2024).
colorectal cancer (5 papers, 2020 to 2026). A primary or metastatic malignant neoplasm that affects the colon or rectum. "In this regard, the upregulation of mitophagy-associated flux mediated by BNIP3L has been reported in human colorectal cancer-derived CSCs." (PMID 38474411, 2024). "Upregulation of BNIP3L-mediated mitophagy has been identified as an escape mechanism against doxorubicin-induced cell death in CD133+/CD44+ CSCs derived from human colorectal cancer." (PMID 38474411, 2024). "Given that BNIP3L/NIX-dependent mitophagy is induced in colorectal cancer stem cells in response to DXR, it is likely that the pathway mediated by PINK1 and Parkin is the one mainly induced by DXR in BC cells." (PMID 38514650, 2024). "Increased mitochondrial oxidative stress by radiation induced BNIP3- and BNIP3L-mediated mitophagy to protect colorectal cancer cells from radiation-induced cytotoxicity." (PMID 36430876, 2022). "The block of mitophagy by BNIP3L down-regulation enhanced doxorubicin sensitivity in colorectal cancer stem cells." (PMID 31948106, 2020).
melanoma (5 papers, 2018 to 2024). A malignant, usually aggressive tumor composed of atypical, neoplastic melanocytes. "Increased expression of BNIP3L is also positively correlated with patient overall survival (OS) in melanoma." (PMID 37681891, 2023). "As expected, by quantitative real-time PCR analysis, it was demonstrated that α-MSH significantly increased the gene expression of BNIP3 and BNIP3L in B16-F10 melanoma cells exposed to hypoxic condition." (PMID 30062060, 2018). "Finally, it was delineated that α-MSH stimulated the HIF-1α signaling as well as the expression of BNIP3/BNIP3L, thereby promoting the autophagy and apoptosis in melanoma cells." (PMID 30062060, 2018). "Therefore, the present study unveiled a unique function of autophagy in promoting cell death during POMC-mediated melanoma suppression via α-MSH/HIF-1α/BNIP3/BNIP3L signaling pathway." (PMID 30062060, 2018). "A subpopulation with high HIF1α expression not only showed significantly higher expression of the canonical HIF1 target BNIP3L, but also of PD-L1 (CD274), as compared to a melanoma subpopulation with low HIF1α expression." (PMID 34268602, 2022). "BNIP3L recruits TR3 to mitochondria, leading to autophagic cell death in melanoma." (PMID 39524226, 2024). "Because of the Bcl-2 family such as BNIP3 and BNIP3L were triggered by HIF-1α in autophagic process, we next evaluated whether α-MSH modulated the Bcl-2 family gene expression in melanoma cells during hypoxia." (PMID 30062060, 2018).
Alzheimer disease (4 papers, 2022 to 2025). A progressive, neurodegenerative disease characterized by loss of function and death of nerve cells in several areas of the brain leading to loss of cognitive function such as memory and language. "The mitochondrial dynamics and mitophagy are also impaired during thedevelopment of Alzheimer’s disease.This is evidenced by alterations in the expression of the ATG5, Beclin1, LC3A,LC3B, PINK1, TERT, BCL2, and BNIP3L genes detected in a mouse model of AD." (PMID 41479568, 2025).
colon cancer (4 papers, 2016 to 2024).
glioma (4 papers, 2012 to 2022). A benign or malignant brain and spinal cord tumor that arises from glial cells (astrocytes, oligodendrocytes, ependymal cells). "It was reported that gga-miR-30c-5p inhibited glioma proliferation and invasion via targeting Bcl-2 and regulated cisplatin-induced apoptosis of renal tubular epithelial cells via targeting Bnip3L and Hspa5." (PMID 35632731, 2022). "Strikingly, a similar mechanism (BNIP3/BNIP3L-mediated autophagic cell death) has also been proposed for ATO in non-GSC glioma cells, indicating that Gos and ATO might target overlapping pathways to promote cell demise of GSCs." (PMID 30871073, 2019). "In fact, we could recently show that HMOX-1 is induced after Gos-mediated mitochondrial dysfunction in non-GSC glioma cells and that this is accompanied by induction of BNIP3 and Nix (BNIP3L), leading to an autophagic type of cell death." (PMID 30871073, 2019).
liver cancer (4 papers, 2020 to 2025). An epithelial or non-epithelial malignant neoplasm that arises from the liver. "Conversely, intervening the BNIP3L-dependent mitophagy by specific genetic intervention with siBNIP3L resulted in the decrease of liver cancer stemness and the ability of colony formation in HBx-expressing MHCC-97H cells." (PMID 32168902, 2020). "Our research provided a novel mechanism for the stemness of hepatic cancer cells conferred by HBx and raised BNIP3L as a possible therapeutic target for liver cancer stem cells (LCSCs)-associated HCC." (PMID 32168902, 2020). "Studies have found that the HBV X protein (HBx), encoded by the HBV X gene for HBV replication, transactivats HIF-1α, inducing BCL2 Interacting Protein 3 Like (BNIP3L)-dependent mitophagy and upregulating glycolytic metabolic reprogramming, thereby enhancing the liver cancer stem cell phenotype." (PMID 39980550, 2025). "We found that anti-HBx could reduce the liver cancer stemness, BNIP3L-dependent mitophagy, and glycolysis metabolism reprogramming in HBx-expressing HCC cells." (PMID 32168902, 2020). "In the studies of mechanism, we proposed a positive feedback loop that HBx upregulated glycolytic metabolism reprogramming through BNIP3L-dependent mitophagy mediated by HIF-1α transactivation, and consequently enhanced the liver cancer stemness phenotypes." (PMID 32168902, 2020).
ovarian carcinoma (4 papers, 2003 to 2025). A malignant neoplasm originating from the surface ovarian epithelium. "Up-regulation of miR-30d contributes to ovarian cancer development by suppressing Beclin1, BNIP3L, ATG12, ATG5, ATG2 directly and inhibiting LC3-I conversion to LC3-II." (PMID 27825125, 2016). "In ovarian cancer, the oncomiR miR-30d was illustrated to impair autophagy by suppressing a multitude of autophagy-related genes including Beclin1, BNIP3L, ATG12, ATG5, ATG2 directly and inhibiting LC3-I conversion to LC3-II." (PMID 27825125, 2016). "Considering its function and location, BNIP3L is a strong candidate for the breast and/or ovarian cancer tumour suppressor gene located at 8p21." (PMID 12610513, 2003). "BNIP3L expression was analysed by both RT–PCR and Northern blot analysis in breast and ovarian cancer cell lines, as well as in cell lines derived from the corresponding normal epithelial cells." (PMID 12610513, 2003). "BNIP3L expression was also examined by Northern blot analysis in a subset of 16 ovarian cancer cell lines." (PMID 12610513, 2003). "BNIP3L expression was assessed by both RT–PCR and Northern blot analysis in breast and ovarian cancer cell lines and found to be expressed at similar levels relative to expression in their respective normal epithelial cell lines." (PMID 12610513, 2003). "BNIP3L was expressed by all the ovarian cancer cell lines, but the level of expression was reduced to approximately half that of HOSE 17.1 in six of the 16 cancer cell lines." (PMID 12610513, 2003). "Analysis of microsatellite markers near the BNIP3L locus detected frequencies of LOH of 43% (D8S137) and 46% (D8S1048) in the ovarian cancers." (PMID 12610513, 2003).
Sepsis (4 papers, 2020 to 2025). Sepsis is defined as life-threatening organ dysfunction caused by a dysregulated host response to infection. "MiR-133a can reduce heart damage caused by sepsis by targeting BNIP3L." (PMID 37724124, 2023). "Our study results showed that the expression level of BNIP3L in the hippocampus and mitochondria of mice were reduced after sepsis." (PMID 36569834, 2022). "In this study, we only explored the relationship between HIF 1a and BNIP3L pathways and sepsis mice in the acute phase, but the long-term relationship with sepsis mice is still unclear." (PMID 36569834, 2022). "Compared with the control group and the sham group, the number of expressions of HIF-1α increased, and BNIP3L decreased significantly in the sepsis group." (PMID 36569834, 2022). "In this study, we found abnormal expression of HIF 1a, BNIP3L protein, and gene in the hippocampus and mitochondrion of sepsis." (PMID 36569834, 2022). "After the HIF 1a inhibitor was used to inhibit the expression of HIF 1a and increase the expression of BNIP3L, the damage to hippocampus structures and mitochondrial structure was significantly reduced, and the cognitive function of sepsis mice were significantly improved." (PMID 36569834, 2022). "There may be other potential mechanisms regulating BNIP3L expression in sepsis, which may be attributed to ubiquitination." (PMID 36569834, 2022). "Compared with the sepsis group, the number of expressions of HIF 1a decreased, and BNIP3L expression increased after the administration of HIF-1α inhibitors." (PMID 36569834, 2022).
amyotrophic lateral sclerosis (3 papers, 2021 to 2025). Amyotrophic lateral sclerosis (ALS) is a neurodegenerative disease characterized by progressive muscular paralysis reflecting degeneration of motor neurons in the primary motor cortex, corticospinal tracts, brainstem and spinal cord. "BNIP3L upregulation was found in the cerebrospinal fluid of patients suffering from amyotrophic lateral sclerosis (ALS), a degenerative disorder of the motor neurons." (PMID 34930907, 2021). "For example, the reactive (and non-apoptotic) astrocytes that contribute to disease pathology in a mouse model of Amyotrophic Lateral Sclerosis (ALS) have increased expression of the BH3-only proteins, Bid, Hrk and Bnip3L." (PMID 35281082, 2022).
cervical cancer (3 papers, 2003 to 2024). A primary or metastatic malignant neoplasm involving the cervix. "BNIP3L reportedly induces cell death by altering mitochondrial membrane permeability and has been found to suppress clonicity in soft agar in cervical cancer cell lines." (PMID 12610513, 2003). "Further evidence for a possible tumour suppressor role of the BNIP3L gene is provided by experiments showing that the clonicity in soft agar of cervical cancer cell lines was suppressed after transfection of the BNIP3L gene." (PMID 12610513, 2003).
depression (3 papers, 2024 to 2025). "Disruptions in this pathway play a major role in depression, particularly those involving the mitophagy receptor NIX (BNIP3L)." (PMID 40806735, 2025).
diabetes (3 papers, 2017 to 2025). "This study offers novel insights into the luteolin’s therapeutic potential in DR, particularly activating mitophagy through the SQSTM1/BNIP3L axis, which expands the scope of natural compounds in addressing this sight-threatening complication of diabetes." (PMID 40635752, 2025). "FOXO family proteins play a vital role in the development of muscle atrophy by activating the ubiquitin-mediated proteolysis pathways including the regulation of FBXO32/Atrogin-1 and TRIM63/MuRF1, and dependently regulate BNIP3L and GABARAPL1 in a STZ-diabetes model." (PMID 32806520, 2020).
heart failure (3 papers, 2017 to 2022). Inability of the heart to pump blood at an adequate rate to meet tissue metabolic requirements. "In vivo, BNIP3L was found to participate in the progression of heart failure in adult rats with TAC using specifically ablation in cardiomyocytes (KO) and conditionally overexpressed it in the heart." (PMID 28507335, 2017). "Together, these data suggest an important role and molecular mechanism for BNIP3L in CFs during pressure overload-induced heart failure." (PMID 28507335, 2017). "To explore the changes in BNIP3L expression during heart failure, we detected its expression levels by western blot and found that they were dramatically increased after 4 weeks of AAC." (PMID 28507335, 2017). "We prove for the first time that the expression of BNIP3L is significantly increased in the CFs of rats undergoing pressure overload-induced heart failure." (PMID 28507335, 2017). "Further exploration of the unknown functions of BNIP3L and the related signaling mechanisms of fibrosis may provide new insights into future therapeutic targets for heart failure." (PMID 28507335, 2017). "Besides the increase of BNIP3L in cardiomyocytes during pressure overload-induced heart failure, our findings showed that BNIP3L significantly increased in CFs during pressure overload-induced heart failure in vivo and NE-induced fibrosis model in vitro." (PMID 28507335, 2017). "This study suggests a potential link between BNIP3L and cardiac fibrosis in CFs, which may improve our understanding of the molecular mechanisms that are involved in pressure overload-induced heart failure." (PMID 28507335, 2017). "BNIP3L is up-regulated in pressure overload-induced heart failure and has been reported to play an important role in cardiomyocyte apoptosis; however, its involvement in cardiac fibroblasts (CFs) remains unknown." (PMID 28507335, 2017). "Taken together, our findings demonstrated that the increase of BNIP3L expression is induced by the PKC signaling pathway, which is activated by the specific binding of NE to α- or β-AR, during pressure overload-induced heart failure." (PMID 28507335, 2017).
intracerebral hemorrhage (3 papers, 2021 to 2023). A cerebrovascular disorder characterized by bleeding into one or both cerebral hemispheres including the basal ganglia and the cerebral cortex. "In contrast to studies on ischemic and traumatic brain injuries, there is a paucity of data indicating the involvement of BNIP3L-mediated mitophagy in intracerebral hemorrhage." (PMID 34930907, 2021).
schizophrenia (3 papers, 2020 to 2022). A major psychotic disorder characterized by abnormalities in the perception or expression of reality. "Common SNPs located in or near BNIP3L were found to be genome-wide significantly associated with schizophrenia in recent genome-wide association studies." (PMID 32393399, 2020). "The three common variants significantly associated with schizophrenia in our study are located in the 3′-UTR of the BNIP3L gene." (PMID 32393399, 2020). "In this study, we performed targeted next-generation sequencing for all exons and un-translated region (UTR) of BNIP3L gene in 1806 patients with schizophrenia and 998 healthy controls to identify potential pathogenic mutations of BNIP3L gene in schizophrenia." (PMID 32393399, 2020). "All the results further confirmed that BNIP3L gene is a susceptibility gene of schizophrenia, but further functional validations are needed for understanding the role of BNIP3L in the pathogenesis of schizophrenia." (PMID 32393399, 2020). "We found rs147389989 in the BNIP3L gene was significantly associated with schizophrenia, and we searched for this locus in the SZDB database." (PMID 32393399, 2020). "In our results, we found three rare nonsynonymous mutations in the BNIP3L gene, c.52A>G, c.167G>A and c.313A>T, carried by eight patients with schizophrenia." (PMID 32393399, 2020). "In BNIP3L, we found that the number of total rare nonsynonymous mutation carriers in schizophrenia cases and healthy controls were significantly different." (PMID 32393399, 2020). "Three rare nonsynonymous mutations, BNIP3L (NM_004331): c.52A>G, c.167G>A and c.313A>T, were identified in schizophrenia cases, and two of them were newly reported." (PMID 32393399, 2020). "The results of the gene-based association analysis showed that the number of nonsynonymous mutations carried by schizophrenia patients was significantly more than healthy controls, which further confirmed that the BNIP3L gene is a susceptibility gene of schizophrenia." (PMID 32393399, 2020). "The results of meta-analyses and the haplotype analysis further confirmed that rs1042992 and rs17310286 located in 3′-UTR of BNIP3L gene were significantly associated with schizophrenia and provided more evidence for BNIP3L gene as a candidate gene for schizophrenia." (PMID 32393399, 2020). "Our results provided additional evidence that BNIP3L was a susceptibility gene of schizophrenia." (PMID 32393399, 2020). "Our research presented a comprehensive mutation spectrum of BNIP3L gene in schizophrenia." (PMID 32393399, 2020). "Recent research about comparative genetic architectures of schizophrenia also revealed that intron variant of BNIP3L gene, rs117325001, was significantly associated with schizophrenia in a fixed-effect meta-analysis including individuals from East Asian and European ancestries." (PMID 32393399, 2020). "Interestingly, an emerging study revealed BNIP3L mutations in human schizophrenia." (PMID 34930907, 2021). "Targeted sequencing for BNIP3L gene among more patients with schizophrenia and more functional validations are considered to be necessary for further understanding the etiology correlated with BNIP3L in schizophrenia." (PMID 32393399, 2020). "We performed targeted sequencing for all exons and un-translated regions of BNIP3L gene among 1806 patients with schizophrenia and 998 healthy controls of Han Chinese origin." (PMID 32393399, 2020). "It is suggested that the 3′-UTR of the BNIP3L gene may play a crucial role in schizophrenia." (PMID 32393399, 2020).
triple-negative breast carcinoma (3 papers, 2020 to 2024). An invasive breast carcinoma which is negative for expression of estrogen receptor (ER), progesterone receptor (PR), and human epidermal growth factor receptor 2 (HER2). "However, the BNIP3L gene is still of interest and a recent publication suggested a BNIP3L dependent pathway to be a target for cancer therapy in a subgroup of triple negative breast cancer." (PMID 35267517, 2022).
acute myeloid leukemia (2 papers, 2021). Acute myeloid leukemia (AML) is a group of neoplasms arising from precursor cells committed to the myeloid cell-line differentiation. "Similarly, higher BNIP3L expression is associated with a better prognosis of acute myeloid leukemia (AML) and sensitized decitabine-induced cell demise without inducing apoptosis." (PMID 34930907, 2021).
brain injury (2 papers, 2021). Acute and chronic (see also brain INJURIES, CHRONIC) injuries to the brain, including the cerebral hemispheres, CEREBELLUM, and brain STEM. "Yuan and colleagues in 2017 demonstrated the neuroprotective roles of BNIP3L against ischaemic brain injury through the regulation of mitophagy." (PMID 33496385, 2021).